RIPK1 (receptor interacting serine/threonine kinase 1)
Diseases named in the same sentence as RIPK1 in open-access papers (continued):
Sharing a sentence is not in itself a finding about the gene and the disease.
infectious disease (1 paper, 2021). A disorder directly resulting from the presence and activity of a microbial, viral, or parasitic agent in humans. "Small molecules that inhibit necroptosis by targeting the kinase activity of RIPK1, one of the main upstream conduits to MLKL activation, have shown promise in several murine models of non-infectious disease and in phase II human clinical trials." (PMID 34071602, 2021).
neuromuscular disease (1 paper, 2023). "Treatment with a candidate ALS drug, the receptor-interacting protein kinase-1 (RIPK1)-inhibitor necrostatin-1, rescues these phenotypes in a dose-dependent manner, highlighting the potential of this platform to screen novel treatments for neuromuscular diseases." (PMID 37619554, 2023).
peripheral neuropathy (1 paper, 2022). A disorder affecting the peripheral nervous system. "This research highlighted a previously unrecognized molecular mechanism of RIPK1 in response to oxidative stress-induced injury in peripheral neuropathy." (PMID 36438920, 2022). "In our study, we found that RIPK1 activation was closely associated with mitochondria in RSC96 cells, providing molecular evidences to the pathogenesis of mitochondrial dysfunction induced peripheral neuropathy." (PMID 36438920, 2022). "The conversion of the changes of RIPK1 and ROS in different cell type including Schwann cells hints at a complicated regulatory network between them, which might influence the targeting efficiency in the treatment of peripheral neuropathy." (PMID 36438920, 2022).
RIPK1 also shares sentences with these, for which no sentence is quoted: bronchiolitis (3 papers); cutaneous lupus erythematosus (3); histiocytic lymphoma (3); ischemia reperfusion injury (3); lysosomal storage disease (3); viral diseases (3); acute lung injury (2); acute respiratory distress syndrome (2); adenocarcinoma (2); adrenocortical cancer (2); bladder urothelial carcinoma (2); cervical squamous cell carcinoma (2); Colon (2); enteritis (2); malaria (2); myocardial ischemia (2); prostate adenocarcinoma (2); retinal (2); rhabdomyosarcoma (2); septic shock (2); Acidosis (1); acute graft versus host disease (1); acute lymphoblastic leukemia (1); acute monocytic leukaemia (1); acute myocardial infarction (1); acute T-cell leukemia (1); acute-on-chronic liver failure (1); age-related macular degeneration (1); alcohol (1); alcoholic liver diseases (1).
A further 92 diseases each share a sentence with RIPK1 in 1 paper.